KPNA1 (karyopherin subunit alpha 1)
Description:
Functions in nuclear protein import as an adapter protein for nuclear receptor KPNB1. Binds specifically and directly to substrates containing either a simple or bipartite NLS motif. Docking of the importin/substrate complex to the nuclear pore complex (NPC) is mediated by KPNB1 through binding to nucleoporin FxFG repeats and the complex is subsequently translocated through the pore by an energy requiring, Ran-dependent mechanism. At the nucleoplasmic side of the NPC, Ran binds to importin-beta and the three components separate and importin-alpha and -beta are re-exported from the nucleus to the cytoplasm where GTP hydrolysis releases Ran from importin. The directionality of nuclear import is thought to be conferred by an asymmetric distribution of the GTP- and GDP-bound forms of Ran between the cytoplasm and nucleus. Mediator of PR-DUB complex component BAP1 nuclear import; acts redundantly with KPNA2 and Transportin-1/TNPO1. (Microbial infection) In vitro, mediates the nuclear import of human cytomegalovirus UL84 by recognizing a non-classical NLS.
Synonyms: NPI-1; RCH2; SRP1; IPOA5
Tractability: PROTAC: UniProt records ubiquitination sites on it; ubiquitination databases record sites on it; its protein half-life has been measured.
Gene: Protein-coding gene on chromosome 3 (122,421,902 to 122,514,947, reverse strand). Ensembl gene ENSG00000114030.
Subcellular location: Cytoplasm; Nucleus
Subcellular location (Human Protein Atlas): Nucleoplasm; Cytosol
Pathways (Reactome):
Disease: Inhibition of nitric oxide production; Integration of provirus; Maturation of DENV proteins; NS1 Mediated Effects on Host Pathways; Transport of Ribonucleoproteins into the Host Nucleus; Vpr-mediated nuclear import of PICs
Immune System: ISG15 antiviral mechanism; Interferon alpha/beta signaling
DNA Replication: Assembly of the ORC complex at the origin of replication
Programmed Cell Death: Apoptosis induced DNA fragmentation
Gene Ontology:
Molecular function: nuclear import signal receptor activity; protein binding; nucleocytoplasmic carrier activity
Biological process: NLS-bearing protein import into nucleus; postsynapse to nucleus signaling pathway; regulation of DNA recombination; protein import into nucleus
Cellular component: cytoplasm; cytosol; NLS-dependent protein nuclear import complex; nucleoplasm; nucleus; dendrite; nuclear pore; glutamatergic synapse; postsynaptic density
Genetic constraint (gnomAD): Loss-of-function variants: 5 observed, 36.67 expected, observed/expected ratio (o/e) 0.14, 90% interval 0.07 to 0.29. The upper end of that interval is the gene's LOEUF score, 0.29, which puts it in group 1 of 6, group 1 being the genes least tolerant of losing a copy. Missense variants: 216 observed, 392.25 expected, observed/expected ratio (o/e) 0.55, 90% interval 0.49 to 0.62. Synonymous variants: 124 observed, 145.25 expected, observed/expected ratio (o/e) 0.85, 90% interval 0.74 to 0.99.
Homologues: Orthologues: chimpanzee KPNA1 (99% identical), macaque KPNA1 (99% identical), dog KPNA1 (99% identical), pig KPNA1 (99% identical), rabbit KPNA1 (99% identical), guinea pig KPNA1 (99% identical), mouse Kpna1 (98% identical), rat Kpna1 (96% identical), tropical clawed frog kpna1 (94% identical), zebrafish kpna1 (85% identical), Drosophila melanogaster Kap-alpha1 (62% identical). Paralogues in human: KPNA6 (81% identical), KPNA5 (80% identical), KPNA2 (46% identical), KPNA4 (46% identical), KPNA3 (45% identical), KPNA7 (40% identical).
Diseases named in the same sentence as KPNA1 in open-access papers:
KPNA1 is named in the same sentence as 25 diseases in open-access papers, as found by Europe PMC text mining. Sharing a sentence is not in itself a finding about the gene and the disease. The quoted sentences say what the papers report.
schizophrenia (5 papers, 2013 to 2025). A major psychotic disorder characterized by abnormalities in the perception or expression of reality. "In these mice we reported that social isolation further exacerbated the schizophrenia-related behavioral abnormalities caused by Kpna1 KO21." (PMID 38336912, 2024). "In this study, we created a G × E interaction model for schizophrenia-like behavior using Kpna1 deficiency and adolescent PCP treatment as genetic and environmental factors, respectively." (PMID 38336912, 2024). "We found that subchronic administration of PCP induced vulnerability and behavioral abnormalities consistent with the onset of schizophrenia in Kpna1-deficient mice." (PMID 38336912, 2024). "Here, we found that subchronic administration of phencyclidine, a psychotropic drug, induced vulnerability and behavioral abnormalities consistent with the symptoms of schizophrenia in Kpna1-deficient mice." (PMID 38336912, 2024). "De novo mutations in Kpna1 have been identified using genome-wide association studies in humans with schizophrenia; however, it remains unclear how KPNA1 contributes to schizophrenia pathogenesis." (PMID 38336912, 2024). "In humans, a de novo mutation of the KPNA1 (human Importin α5) gene has been linked with schizophrenia; however, the precise roles of KPNA1 in disorder-related behaviors are still unknown." (PMID 34767585, 2021). "Interestingly, in humans, examination of the exomes of schizophrenia patients have identified a de novo nonsense mutation in KPNA1 (human importin α5 gene), suggesting a possible link between KPNA1 and schizophrenia." (PMID 34767585, 2021). "The KPNA1 mutations identified in patients with schizophrenia are located outside of the conventional NLS recognition region, implying that KPNA1 plays a role in schizophrenia development via mechanisms other than nucleocytoplasmic transport." (PMID 38336912, 2024). "In this study, we further analyzed G × E interactions in Kpna1 KO mice, which are used as a model for schizophrenia-like behavioral abnormalities." (PMID 38336912, 2024). "NSF is known to be involved in PD whereas KPNA1 is known to be involved in several neurological disorders including autism and schizophrenia." (PMID 28899360, 2017). "Our findings suggest that our PCP treated Kpna1 KO mouse model may aid in furthering developing a G × E interaction model of schizophrenia." (PMID 38336912, 2024). "KPNA1 dysfunction in the NAc contributes to schizophrenia development." (PMID 38336912, 2024). "In addition, we used this model to investigate the role of KPNA1 in the pathophysiology of schizophrenia-related behaviors by focusing on G × E interactions." (PMID 38336912, 2024). "The enriched function of G × E interacting genes is clearly different in the PFc and NAc, and enrichment in the NAc is associated with behavioral abnormalities, suggesting that increased vulnerability to PCP in the NAc following Kpna1 KO is involved in the development of schizophrenia." (PMID 38336912, 2024). "De novo mutations in Kpna1 in patients with schizophrenia are heterozygous and may not result in completely non-functional mutations." (PMID 38336912, 2024).
breast carcinoma (4 papers, 2015 to 2023). "For example, a study identified high KPNA1 expression in breast cancer, which was associated with poor overall survival (OS)." (PMID 35991543, 2022). "For example, KPNA1 was shown to modulate the nuclear import of NCOR2 splicing variant BQ323636.1 and thus promote tamoxifen resistance in breast cancer." (PMID 35991543, 2022). "We first investigated the endogenous expression of KPNAs gene (KPNA1 to 7) in 11 breast cancer cell lines and normal mammary gland tissue via semi-quantitative RT-PCR." (PMID 26052702, 2015). "The results showed that KPNA1 to 6 was highly expressed in all 11 breast cancer cell lines as well as in normal mammary gland tissue, while focal KPNA7 expression was observed in the SK-BR-3 and HCC1143 cell lines." (PMID 26052702, 2015). "The association of the six top-ranked karyopherins (KPNA2, XPOT, CSEL1, KPNA1, KPNA4, and TNPO1) in the breast cancer datasets from Oncomine was analyzed using a Kaplan-Meier Plotter." (PMID 37928256, 2023). "We found that overexpressed PHB2 interacted with KPNA1, KPNA5, and KPNA6, thereby leading to the E2-dependent translocation of PHB2 into the nuclei of breast cancer cells." (PMID 26052702, 2015). "Here we report the mechanism by which BIG3 blocks the nuclear translocation of PHB2 via interactions with multiple karyopherin alpha (KPNA) proteins, including KPNA1, KPNA5, and KPNA6, in ERα-positive breast cancer cells." (PMID 26052702, 2015). "In breast cancers, however, BIG3 captures PHB2 through its KPNA (KPNA1, KPNA5, and KPNA6)-binding region(s), thereby inhibiting the E2-dependent suppressive ability of PHB2." (PMID 26052702, 2015).
Anxiety (3 papers, 2021 to 2024). Intense feelings of nervousness, tension, or panic often arise in response to interpersonal stresses. "In our behavioral test battery, Kpna1 deficient groups exhibited a significant reduction in anxiety-like behavior in the EPM, a significant reduction in PPI levels, as well as an increased sensitivity to methamphetamine induced hyperlocomotion." (PMID 38336912, 2024). "All behavioral alterations caused by Kpna1 deletion and G x E interaction, other than decreased anxiety-like behavior, were identified here for the first time." (PMID 34767585, 2021). "This is the first report of increased depression-like behavior in Kpna1 deficient mice, and stands in contrast to the decreased anxiety-like behavior observed in the EPM." (PMID 34767585, 2021). "Similar to previous reports, the Kpna1 KO genotype was associated with decreased measures of anxiety (increased open arm activity) in the EPM, increased sensitivity to a psychostimulant (methamphetamine), and decreased PPI of sensorimotor response to an acoustic startle stimulus." (PMID 38336912, 2024). "Behaviorally, Kpna1 KO mice have been reported to exhibit reduced anxiety-like behaviors and impaired startle responses, indicating that KPNA1 may play a role in controlling behaviors associated with psychiatric disorders." (PMID 34767585, 2021). "Administering phencyclidine to Kpna1 knockout mice during an equivalent adolescence stage in humans revealed reduced anxiety-like behavior and a substantial increase in motor activity." (PMID 38336912, 2024). "Two-way ANOVA revealed a significant influence on all measures of behavior assessed using the EPM test, where both Kpna1 KO groups showed decreased levels of anxiety-like behavior compared to the WT groups." (PMID 38336912, 2024). "In the EPM, Kpna1 KO mice demonstrated a significant decrease in anxiety-like behavior compared with WT mice." (PMID 34767585, 2021). "A previous study has reported that Kpna1 KO mice show decreased anxiety-like behavior (in EPM and OFT), which was attenuated by either administration of a Sphk1 inhibitor PF-543, or rescue of Kpna1 in the ventral hippocampus." (PMID 34767585, 2021). "Taken together, the results of the behavioral test battery indicate that the G × E interaction in Kpna1 KO mice is characterized by decreased anxiety-like behavior (increased novelty induced locomotor activity) in the OFT, as well as increased locomotor activity in the Y-maze test." (PMID 38336912, 2024). "However, further behavioral phenotyping of Kpna1 KO mice has revealed psychiatric disorder-related behavioral deficits such as a prominent reduction in anxiety-like behavior and reduced acoustic startle response." (PMID 38336912, 2024). "To investigate the effects of Kpna1 deletion and adolescent isolation on psychiatric-disorder related behaviors, we designed a behavioral test battery to assess anxiety-like behaviors(OFT, EPM), Memory (Y-Maze, NORT, IA), sensorimotor gating (PPI), and depression-like behavior (FS)." (PMID 34767585, 2021). "In our study, we found Kpna1 deletion decreases anxiety-like behavior, impairs short-term memory and sensorimotor gating, and increases depression-like behavior, suggesting that hypofunction of KPNA1 results in behavioral changes associated with psychiatric disorders." (PMID 34767585, 2021). "Importin α1/KPNA1 is a member of the Importin α family widely present in the mammalian brain and has been characterized as a regulator of neuronal differentiation, synaptic functionality, and anxiety-like behavior." (PMID 34767585, 2021).
memory impairment (2 papers, 2021 to 2024). "Surprisingly, memory impairment-related genes were enriched in the NAc of PCP-treated Kpna1 KO mice." (PMID 38336912, 2024). "Moreover, a G x E interaction between Kpna1 deletion and social isolation stress was observed in aversive learning and/or memory impairments and depression-like behavior in the IA and FS tests, respectively." (PMID 34767585, 2021).
Alzheimer disease (1 paper, 2024). A progressive, neurodegenerative disease characterized by loss of function and death of nerve cells in several areas of the brain leading to loss of cognitive function such as memory and language. "We found that DEGs identified in the PFc of PCP-treated Kpna1 KO mice and PCP-treated WT mice differed from other DEGs with regards to their positive normalized enrichment scores for Alzheimer's disease, Parkinson's disease, and Huntington's disease." (PMID 38336912, 2024).
cervical cancer (1 paper, 2022). A primary or metastatic malignant neoplasm involving the cervix. "Our results suggest the downregulation of KPNA1 expression is related to the malignant degree of cervical cancer and is closely associated with the proliferation of cervical cancer cells." (PMID 35991835, 2022). "The data confirmed that the downregulation of KPNA1 expression was associated with the degree of malignancy of cervical cancer." (PMID 35991835, 2022). "The purpose of the present study was to evaluate the expression levels of KPNA1 in cervical cancer samples of patients using immunohistochemistry and confirm their potential diagnostic utility as a novel molecular marker for discriminating among different malignant grades of cervical cancer." (PMID 35991835, 2022). "We collected the medical data of 106 patients with cervical cancer and investigated the protein expression of KPNA1 and KPNA2 by immunohistochemistry and western blot." (PMID 35991835, 2022). "In conclusion, this study shows that the expression of KPNA1 is decreased in cervical cancer tissues and cells." (PMID 35991835, 2022). "To further confirm the correlation between KPNA1/2 levels and the degree of malignancy of cervical cancer, we further detected the expression of KPNA1 and KPNA2 in cervical tumor tissues with different histopathologic grades by immunohistochemical staining." (PMID 35991835, 2022). "Here, we found the direct effect of KPNA1 on cervical cancer cell proliferation, which is related to transporting IRF3 to the nucleus." (PMID 35991835, 2022). "We also counted the KPNA1-and KPNA2-positive cells in normal and cervical cancer tissues and calculated the pathological scores associated with KPNA1/2 expression." (PMID 35991835, 2022). "The results revealed a significantly lower expression of KPNA1 in cervical cancer compared to normal tissue." (PMID 35991835, 2022). "The level of KPNA1 is further decreased with an increase in the degree of cervical cancer malignancy." (PMID 35991835, 2022). "We also found that the proportion of cells with KPNA1-positive staining was considerably lower, and the intensity of the staining was markedly weaker in the cervical cancer cases than in the normal controls." (PMID 35991835, 2022). "To determine whether KPNA1 had functional relevance for cervical cancer cell growth, we overexpressed KPNA1 by transfecting the plasmid pCMVTNT-T7-KPNA1 into Hela cells." (PMID 35991835, 2022). "It suggests that KPNA1 may be a potential therapeutic target for cervical cancer patients, although this remains need to be supported by more evidence." (PMID 35991835, 2022). "Moreover, variations in the extent and intensity of KPNA1-positive staining were observed within different histopathologic grades of cervical cancer, ranging from weak to strong reactivity." (PMID 35991835, 2022). "Our findings suggest that KPNA1 may potentially serve as both a biomarker and therapeutic target for patients with cervical cancer." (PMID 35991835, 2022). "The objective of this study was to investigate the expression of KPNA1 and KPNA2 in cervical cancer tissue with different histologic grades and cell lines, as well as the effects of the KPNA1 expression level on Hela cell proliferation." (PMID 35991835, 2022). "In addition, the up-regulation of KPNA1 clearly increases the level of nuclear IRF3 and suppresses the proliferation of cervical cancer cells." (PMID 35991835, 2022). "Moreover, KPNA1 expression was moderately downregulated and extensively decreased in the Grade II and III cervical cancer specimens, respectively." (PMID 35991835, 2022). "We then detected the expression of KPNA1 and KPNA2 in human cervical carcinoma Hela and C33A cells." (PMID 35991835, 2022).
cervical cancer (continued). "In our another paper that has been published recently, we have clarified that E6 protein induced by HPV16/18 could significantly promoted the ubiquitination and degradation of KPNA1 that resulted in the suppression of nuclear transport of phosphorylated STAT1 and apoptosis in cervical cancer cells." (PMID 35991835, 2022). "The staining results showed that the immunoreactivity for KPNA1 was significantly lower in the cervical cancer tissues than the normal tissues, whereas KPNA2 displayed the opposite trend, with increasing immunostaining in the cervical cancer tissue over the normal tissue." (PMID 35991835, 2022).
cervical tumor (1 paper, 2022). "In this study, we mainly carried out analyses of KPNA1 expression in cervical tumor tissues and cell line." (PMID 35991835, 2022). "Conversely, the KPNA1 level was downregulated in cervical tumor tissue." (PMID 35991835, 2022).
leukemia (1 paper, 2025). A malignant (clonal) hematologic disorder, involving hematopoietic stem cells and characterized by the presence of primitive or atypical myeloid or lymphoid cells in the bone marrow and the blood. "Furthermore, KPNA1 negatively interacted with PPP1CA, a protein linked to poor prognosis, suggesting a potential role of KPNA1 in modulating negative prognostic pathways in leukemia." (PMID 39940906, 2025). "Moreover, GSPT1 interacted with ELAVL1 and EIF4B, proteins associated with favorable AML outcomes, while KPNA1 negatively interacted with PPP1CA, a marker of poor prognosis, suggesting its role in modulating negative prognostic pathways in leukemia." (PMID 39940906, 2025).
ovarian carcinoma (1 paper, 2022). A malignant neoplasm originating from the surface ovarian epithelium. "Our research reveals that KPNA1 has potential for use as a diagnostic biomarker in aggressive ovarian carcinomas." (PMID 35991835, 2022).